OSM (oncostatin M)
Diseases named in the same sentence as OSM in open-access papers (continued):
Sharing a sentence is not in itself a finding about the gene and the disease.
glioma (13 papers, 2011 to 2025). A benign or malignant brain and spinal cord tumor that arises from glial cells (astrocytes, oligodendrocytes, ependymal cells). "Macrophages can directly induce the MES phenotype transition of glioma cells via cytokine-mediated pathways, such as the secretion of oncostatin M (OSM) by macrophages, which activates OSMR on GBM cells and triggers the switch to the MES molecular subtype." (PMID 38398231, 2024). "For example, a recent study employed a co-cultured system between glioma spheres and human macrophages, and identified that macrophages and macrophage-secreted cytokine oncostatin M (OSM) induced a mesenchymal transition in glioma cells." (PMID 38596241, 2023). "Previous studies have evaluated the role of OSMR and its ligand OSM in a range of cancers, including glioma." (PMID 32248843, 2020). "All these results indicate the key role of OSM signaling in glioma progression and invasion, despite some contradictions of these studies." (PMID 31950039, 2019). "OSM, an IL-6 family cytokine in inducing mesenchymal properties in GBM which mediated signaling contributes to aggressive nature associated with mesenchymal features via STAT3 signaling in glioma cells)." (PMID 38159261, 2023). "OSM is a cytokine with multiple, divergent effects on cell proliferation differing among cell types and lines with growth inhibition effects reported in melanoma and glioma cells but stimulation of growth of Kaposi's sarcoma cells." (PMID 21481226, 2011). "High expression of oncostatin M (OSM) receptor OSMR has recently emerged as a poor prognosis factor in several malignancies such as acute myeloblastic leukemia (AML), gliomas, pancreatic, gastric and kidney carcinomas." (PMID 41040517, 2025). "To investigate the association between PLAUR in macrophages and the mediation of MES transition in glioma cells with OSM or ICAM1, we assessed the mRNA expression of OSM and ICAM1 in THP1-derived macrophages following lentiviral shPLAUR or shNT transfection." (PMID 38398231, 2024). "It was observed that TAM cells with high PLAUR expression exhibited increased levels of ICAM-1, OSM, and other molecules known to mediate the MES phenotype of glioma." (PMID 38398231, 2024). "Among these ligands, OSM and ICAM1 have been previously identified as potent molecules inducing MES phenotype transition in glioma cells." (PMID 38398231, 2024). "Overexpression of OSM and OSMR has been detected in various cancers, including gastric, colorectal, breast, and glioma." (PMID 36193073, 2022).
pulmonary fibrosis (12 papers, 2011 to 2025). Chronic progressive interstitial lung disorder characterized by the replacement of the lung tissue by connective tissue, leading to progressive dyspnea, respiratory failure, or right heart failure. "In fibrotic diseases, several of IL-6 family cytokines including IL6 and OSM have been shown to induce pulmonary fibrosis, but the contribution of IL-31/IL-31RA signaling in lung fibrosis has remained unexplored." (PMID 33815402, 2021). "Recently, elevated levels of oncostatin M (OSM) have been reported in the bronchoalveolar lavage fluid of a pulmonary fibrosis animal model and in patients." (PMID 28297588, 2017). "In our study, the OSM mRNA level was significantly upregulated in lung tissues of the early stage of BLM‐induced lung fibrosis mouse model." (PMID 28297588, 2017). "Other members of the IL-6 cytokine family, that signal through glycoprotein 130 (gp130), including oncostatin M (OSM), are also implicated in lung fibrosis, including IPF20." (PMID 28139758, 2017). "Here, we investigated the effect of transient adenoviral overexpression of OSM or IL-6 in mice during bleomycin-induced lung fibrosis." (PMID 29038604, 2017). "Moreover, it was previously shown that OSM enhances liver fibrosis in mice and that OSM is upregulated in patients with pulmonary fibrosis." (PMID 33959646, 2021). "Furthermore, fibronectin, OSM, and SPARC have been reported to participate in pathological situations such as tissue remodeling and pulmonary fibrosis in ARDS." (PMID 34130757, 2021). "Furthermore, OSM stimulated the production of collagen in MRC‐5 fibroblast, suggesting a role for OSM in pulmonary fibrosis." (PMID 28297588, 2017).
melanoma (11 papers, 2011 to 2025). A malignant, usually aggressive tumor composed of atypical, neoplastic melanocytes. "An anti-proliferative role of OSM was reported in immune-deficient mice injected with human melanoma cells and in a chondrosarcoma model, where local intra-tumor overexpression of OSM reduced tumor development and enhanced tumor cell apoptosis through the JAK3/STAT1 axis." (PMID 36077744, 2022). "Since OSM is an interleukin-6 (IL-6) type cytokine to inhibit melanoma proliferation, the loss of OSM gene expression in drug-resistant patients may inhibit the activity of collagen biosynthesis and interleukin-6 family signaling." (PMID 35495152, 2022). "While OSM was initially discovered as an inhibitor of cancer cell growth in melanoma cells, OSM has been shown to play an important role in cancer progression." (PMID 37841259, 2023). "In contrast, VEGFA, TGFβ receptor, NLRP3 inflammasome and Oncostatin M signaling were selectively upregulated, while antigen processing and pattern recognition receptor activity genes were downregulated in melanoma mDC." (PMID 37938561, 2023). "The IL-6 family cytokine Oncostatin M (OSM) was first described as a factor released by U937 lymphoma cells with the ability to inhibit the growth of the human melanoma cells A375 in vitro." (PMID 34769079, 2021). "Although OSM was initially described as an antiproliferative cytokine inhibiting the growth of melanoma, breast cancer, chondrosarcoma, lung adenocarcinoma, and glioblastoma cells, it has also been shown to promote proliferation in various cell lines." (PMID 34769079, 2021). "OSM has been identified as an inhibitor of tumor cell growth in a variety of cancers, including melanoma, ovarian cancer, and glioblastoma carcinomas." (PMID 33541291, 2021). "The interleukin-6-type cytokine oncostatin M (OSM) was initially described as a cytokine with strong growth inhibitory effects on melanoma cells." (PMID 22937020, 2012). "OSM is known to confer multiple, often divergent functions to various cell types including inhibition of melanoma and astroglioma tumor cell growth and stimulation of proliferation of AIDS-related Kaposi's sarcoma cells and fibroblasts." (PMID 21481226, 2011). "Historically, OSM has been identified as a strong inhibitor of melanoma." (PMID 37841259, 2023). "In addition, TGFβ, NLRP3 inflammasome, Oncostatin M and VEGF/VEGFR signaling pathway was enriched in melanoma DC, which has been shown to be inhibitory to DC maturation and function." (PMID 37938561, 2023).
Obesity (10 papers, 2015 to 2026). Accumulation of substantial excess body fat. "In addition to its functions in AT and association with obesity and Type 2 diabetes, OSM has been shown to play a role in a variety of disease conditions." (PMID 33854494, 2020). "In adipose tissue from obese mice, OSMRß has been reported to be increased in the SVF, especially in the F4/80-positive ATMs (adipose tissue macrophages), suggesting that OSM signaling is strongly associated with the pathogenesis of obesity and related metabolic disorders." (PMID 33854494, 2020). "ELISA findings revealed that the levels of interleukin‐6 receptor subunit beta (gp130), oncostatin‐M (OSM), and IL‐6 in serum and hippocampus decreased in obesity, whereas they increased in AD, aligning with the results of the MR Analysis." (PMID 40958408, 2025). "Oncostatin M (OSM) is an immune cell-derived cytokine that is upregulated in adipose tissue in obesity." (PMID 35563078, 2022). "Oncostatin M (OSM) is another proinflammatory cytokine that is elevated in AT in human obesity, and its specific receptor (OSMRβ) is also induced in conditions of obesity and insulin resistance." (PMID 33854494, 2020). "Levels of OSM and its receptor are elevated in AT in conditions of obesity and insulin resistance in mice and man." (PMID 33854494, 2020). "Although OSM has been proposed as a novel therapeutic target for metabolic syndrome, further research is warranted to provide insights into its role in inflammation, insulin resistance, and lipid metabolism in the context of obesity-related metabolic syndrome." (PMID 40076884, 2025). "Therefore, it is reasonable to predict that in obesity, the overexpression of OSM by immune cells, including macrophages, is acting on adipocytes to induce the secretion of inflammatory cytokines that promote infiltration and activation of more macrophages." (PMID 33854494, 2020). "The proteins that were increased in diabetes, including OSM, IL-8, IL-18R, TNFSF14, TNF and IL-6, play roles in obesity, insulin resistance, beta cell function and vascular diabetes complications." (PMID 41175199, 2026). "Oncostatin M (OSM) is a member of the glycoprotein 130 cytokine family that is involved in chronic inflammation and increased in adipose tissue under obesity and insulin resistance." (PMID 35531859, 2022).
colitis (9 papers, 2018 to 2025). Inflammation of the colon. "Notably, genetic OSM deficiency or OSM blockade using an OSMR-gp130 fusion protein attenuates colitis in a dysbiosis-driven model of IBD that is refractory to anti-TNF therapy." (PMID 31156640, 2019). "Consistently, OSM−/− mice displayed reduced colonic pathology and OSM-associated inflammatory modules in the experimental colitis attributing to H. hepaticus and α-IL-10R exposure (Hh+α-IL-10R colitis)." (PMID 32332711, 2020). "OSM knockout mice and OSM neutralization repressed colitis severity." (PMID 35011361, 2021). "Adenovirus (AdV)-induced overexpression of oncostatin M (OSM), a multifunctional cytokine that belongs to the IL-6 subfamily, improved clinical scores in a DSS colitis mouse model." (PMID 41463087, 2025). "Together with similar models, our study demonstrated another mechanism of R. intestinalis in decreasing the secretion of the macrophage-derived oncostatin M (OSM) and maintaining intestinal mucosal permeability to alleviate DSS-induced colitis." (PMID 34881193, 2021).
Sepsis (9 papers, 2020 to 2025). Sepsis is defined as life-threatening organ dysfunction caused by a dysregulated host response to infection. "In our study, we identified several inflammatory factors, including FGF-19, AXIN1, FGF-23, IL-4, OSM, and IL-2, that showed statistically significant associations with sepsis risk using the IVW method in MR analyses." (PMID 39205680, 2024). "OSM levels are elevated in patients with sepsis and septic shock, implicating OSM signaling in sepsis pathophysiology, although its role remains unclear." (PMID 36831019, 2023). "Likewise, oncostatin M (Osm) is identified as an inflammation biomarker in periodontal diseases, sepsis, inflammatory bowel disease." (PMID 32659965, 2020). "The mouse model of cytokine storm syndrome (CSS) or sepsis may be particularly useful for testing this hypothesis, given the important roles of IL6 and OSM in CSS pathogenesis." (PMID 38338642, 2024).
hepatocellular carcinoma (8 papers, 2009 to 2025). A malignant tumor that arises from hepatocytes. "PFKFB3-NF-κB signaling induced the production of CXCL2 and CXCL8 in tumor-infiltrating monocytes, increased levels of CXCL2 and CXCL8 in monocytes and promote infiltration of oncostatin M-producing neutrophils in human hepatocellular carcinoma tissues." (PMID 37253634, 2023). "Studies have demonstrated that OSM overexpression in hepatocellular carcinoma can promote tumor cell invasion and angiogenesis." (PMID 38034950, 2023). "Mouse OSM – in hepatoma cells – cannot activate signaling in human cells, however, it signals comparably to rOSM on rat cells." (PMID 22937020, 2012). "The inflammatory cytokine oncostatin M (OSM) was shown to induce the expression of hypoxia-inducible factor-1 α (HIF-1 α) under normoxic conditions in hepatocytes and hepatoma cells." (PMID 26889381, 2016).
myocardial infarction (8 papers, 2015 to 2025). Gross necrosis of the myocardium, as a result of interruption of the blood supply to the area, as in coronary thrombosis. "Oncostatin M (OSM) is known to be an inflammatory cytokine, and inhibition of OSM signaling inhibits cardiomyocyte remodeling, leading to deterioration of cardiac function after myocardial infarction." (PMID 41018180, 2025). "Oncostatin M (OSM) and leukemia inhibitory factor (LIF) signaling protects the heart after myocardial infarction (MI)." (PMID 35008777, 2021).
asthma (7 papers, 2017 to 2025). "Plenty of research has indicated that OSM is highly expressed in a variety of inflammatory disorders, including chronic rhinosinusitis and asthma." (PMID 36829975, 2023). "Oncostatin M is a regulator of the extracellular matrix in many tissues and is therefore likely to play a role in airway remodeling in asthma." (PMID 36307832, 2022). "Patients with asthma also exhibited high expressions of OSM, whereas there was no expression of OSM in control subjects." (PMID 39796391, 2025). "High levels of OSM mRNA and protein were exhibited in patients with asthma, whereas no OSM was shown in control subjects." (PMID 35723323, 2022).
Insulin resistance (7 papers, 2020 to 2026). Increased resistance towards insulin, that is, diminished effectiveness of insulin in reducing blood glucose levels. "In that study, the researchers also noted a significant positive correlation between oncostatin M levels and both C-reactive protein and homeostasis model assessment of insulin resistance values." (PMID 38397957, 2024). "Additional studies are needed to investigate the relationship between oncostatin M, inflammatory markers, and insulin resistance to gain a better understanding of the role of oncostatin M in metabolism." (PMID 38397957, 2024). "We have previously shown that the pro-inflammatory cytokine oncostatin M (OSM) may contribute to development of hepatic insulin resistance and steatosis and that its production is enhanced by PGE2 in primary rat KC." (PMID 40380177, 2025). "In the context of the inflammation and metabolic parameters, oncostatin M was inversely correlated with C-reactive protein, homeostasis model assessment of insulin resistance, and low-density lipoprotein cholesterol (ρ = −0.353, p = 0.019; ρ = −0.275, p = 0.048; ρ = −0.470, p < 0.001, respectively)." (PMID 38397957, 2024). "In their research, Akarsu M and colleagues suggested that oncostatin M may have contributed to the development of insulin resistance by interacting with specific adipokines, especially in obese patients." (PMID 38397957, 2024). "Therefore, in light of the current literature, we hypothesized that oncostatin M might contribute to the pathophysiology of polycystic ovary syndrome because of its relationship with ovulation, insulin resistance, and inflammation." (PMID 38397957, 2024). "A negative correlation was found between oncostatin M levels and both homeostasis model assessments of insulin resistance and C-reactive protein levels in our study." (PMID 38397957, 2024). "Similarly, the negative correlation between oncostatin M, homeostatic model assessment for insulin resistance, and C-reactive protein values was detected in our study." (PMID 38397957, 2024).
nasal polyps (7 papers, 2021 to 2025). "Oncostatin M (OSM) is also an inflammatory mediator associated with chronic rhinosinusitis with nasal polyps and it promotes epithelial barrier dysfunction." (PMID 34445093, 2021). "OSM expression significantly increased in nasal polyp tissue from patients with chronic rhinosinusitis with nasal polyps and correlated with IL-13 expression in the sinus mucosa." (PMID 40677708, 2025). "OSM and IL-6 were both overexpressed, and TJ (ZO-1 and occludin) expression was decreased in the nasal polyps compared to the control mucosa." (PMID 37047067, 2023). "They reported that OSM mRNA and protein levels were highly increased in nasal polyps obtained from the CRSwNP patients, as compared with those seen in control uncinate tissue (UT)." (PMID 38137445, 2023). "OSM and IL-6 were overexpressed in the nasal polyps when compared to the control mucosa (p < 0.0001)." (PMID 37047067, 2023). "First, we analyzed IL-6 and OSM expression, the secretion of OSM in outer space, and epithelial TJ expression patterns in nasal polyps." (PMID 37047067, 2023). "Both oncostatin M (OSM) and IL-6 are locally produced in nasal polyps and may contribute to pathology by negatively impacting epithelial barrier function." (PMID 40453660, 2025). "We classified the ethmoid sinus mucosa and nasal polyp (NP) samples obtained during surgery into a control group and a CRS group, and we conducted an RT-PCR analysis to determine the mRNA expression levels of OSM and OSMRβ." (PMID 38137445, 2023). "OSM is overexpressed in nasal polyps compared to nonpolypoid nasal mucosa in chronic rhinosinusitis." (PMID 35682987, 2022). "In nasal polyps and in noninflammatory nasal mucosa, we quantified by RT-qPCR the expression of TGF-β1, OSM and IL-4, which are known to be implicated in fibrotic processes." (PMID 35682987, 2022). "TGF-β1, IL-4 and OSM as well as αSMA were overexpressed in nasal polyps when compared to noninflammatory nasal mucosa." (PMID 35682987, 2022).
Arthritis (6 papers, 2014 to 2024). Inflammation of a joint. "In arthritis, oncostatin M (OSM), a cytokine present in synovial fluid and joint tissue, synergizes the action of other inflammatory cytokines (e.g., IL-1, TNF-α, IL-17, lipopolysaccharide (LPS))." (PMID 34834636, 2021). "Past research showed arthritis correlating with osteoclast differentiation, and a recent study indicates that osteoblasts also participate in the inflammation process, OSM being strongly expressed in osteoblasts isolated from femora in arthritics." (PMID 25198901, 2014). "Since anti-OSM antibodies ameliorated murine arthritis when administered before or immediately after the onset of arthritis, it is possible that OSM signaling may be important at the earlier phase of autoimmune arthritis rather than the later phase." (PMID 39080781, 2024). "Both joint swelling and bone erosion were impaired in Osmr∆Fibro mice compared to the control Osmrflox mice in K/BxN serum-transfer arthritis, indicating that OSM signaling in synovial fibroblasts is important for both inflammation and bone destruction in arthritis." (PMID 39080781, 2024). "Since OSM is constitutively expressed in the bone compartment and detected in patients with arthritis pathology, using OSM antibody could decrease cartilage destruction of knee joints in vivo." (PMID 25198901, 2014). "Additionally, OSM expression was higher in the medial tibial periosteum than in the lateral, independent of induction of arthritis." (PMID 33673583, 2021).
heart failure (6 papers, 2016 to 2025). Inability of the heart to pump blood at an adequate rate to meet tissue metabolic requirements. "Within the Ly6clow group of macrophages that proliferates 1 week after TAC, on the other hand, it is the CCR2+ macrophages that are affected by the absence of CD8+T cells and that produce the growth factors (IGF-1, AREG, OSM) which are supposed to be involved in reduced heart failure." (PMID 34745139, 2021). "Finally, we examined the expression of OSM in human heart specimens, which were obtained from heart failure patients." (PMID 31249305, 2019). "Oncostatin M (OSM) is a major mediator of cardiac remodeling in heart failure." (PMID 27803896, 2016). "Our study suggests that bone may also be a source of FGF23 independent of heart failure, e.g. in inflammatory conditions associated with enhanced production of oncostatin M." (PMID 37225713, 2023). "Oncostatin M is part of the interleukin-6 (IL-6) family and regulates remodeling and PTH effects in bone as well as cardiac FGF23 production in heart failure via glycoprotein gp130." (PMID 37225713, 2023).